GLI1 (GLI family zinc finger 1)
Diseases named in the same sentence as GLI1 in open-access papers (continued):
Sharing a sentence is not in itself a finding about the gene and the disease.
tumor (continued). "GEPIA, utilizing tumor tissues from TCGA and normal tissues from GTEx project, revealed the tumor-specific expression patterns of GLI1." (PMID 39483334, 2024). "In clinical trials, GLI1 expression reductions of between 21 and 61.3% over 4 and 26 weeks mostly resulted in moderate decrease of tumor volume." (PMID 38308119, 2024). "GLI1 is a key transcription factor in the SHH pathway, and H. pylori infection reduces the methylation level of the GLI1 promoter region in an m6A-dependent manner, thereby activating the expression of GLI1 and promoting tumor proliferation." (PMID 39434880, 2024). "GANT58 is a small‐molecule inhibitor specific to GLI1, which has significant inhibitory effects on tumor cells in vitro but lacks in vivo and clinical trials." (PMID 38741887, 2024). "Some positivity was also detected for GLI1 protein, 16.7% of tumor samples on average, while other examined proteins of the Hedgehog signaling pathway were mostly undetectable." (PMID 38731849, 2024). "In the compound mouse model, selective deletion of stromal AR expression in Gli1-lineage cells impaired transgenic Myc-induced prostatic epithelial oncogenesis and tumor development." (PMID 39369165, 2024). "The tumor mass itself was found positive for GLI1 and GLI3 in a proportion of samples, while S100A7 and KRT16 were rarely detected." (PMID 38892279, 2024). "Firstly, we evaluated the expression profiles of GLI1/2/3 in different cancer types, analyzed their prognostic and predictive values, and assessed their correlation with tumor-infiltrating immune cells." (PMID 38498906, 2024). "To investigate the correlation between GLI1/2/3, we conducted correlation line analyses in tumor tissues, normal tissues, and tumor cell lines." (PMID 38498906, 2024). "Combining data from TCGA tumor samples and normal tissues from the GETx database showed significant expression of GLI1, GLI2, and GLI3 in 24, 28, and 23 types of cancer, respectively." (PMID 38498906, 2024). "NCI-H1299shNC/NCI-H1299shGli1 cells were injected subcutaneously into the nude mice to establish a xenograft model, and the effect of Gli1 on tumor angiogenesis was further evaluated." (PMID 38493151, 2024). "When HNSCCs are irradiated, there is the activation of GLI1 in the stroma, which contributes to the repopulation of the tumor after therapy and radioresistance." (PMID 38731849, 2024). "Other preclinical studies that used the same mouse model as we did have shown that 60–65% reduction of Gli1 expression after 3 weeks was enough to reduce tumor size and, in some cases, lead to complete tumor regression." (PMID 38308119, 2024). "Our analysis using TIMER2.0 revealed a significant reduction in GLI1 expression in tumor tissues compared to their matched normal controls in several cancer types, including BLCA, BRCA, KIRP, THCA, and UCEC." (PMID 39483334, 2024). "We report that NRP2-expressing cells serve as a hub for NO production, by enhancing NOS2 transcription via Gli1, which creates local fields within the tumor that can protect the cells from radiation." (PMID 39352757, 2024). "GLI1-altered neoplasms have a moderate degree of variability as they are seen in a broad range of anatomic sites and amongst people of all ages." (PMID 39720383, 2024). "As such, the implications of the AR and Gli1 interactions through stromal and epithelial cells in both normal and tumor status should be further investigated." (PMID 39369165, 2024). "Tumor-derived GLI1 sustains expansion and invasion of PMN-MDSCs in vitro, and promotes their immunosuppressive activity on T cells, inhibiting their effector capability, as demonstrated by the reduced production of IFNγ by CD4 + and CD8 + T cells." (PMID 39090759, 2024). "Similar effects were observed when Ewing Sarcoma cells were treated with ATO, reducing GLI1 levels, resulting in decreased tumor growth." (PMID 38612911, 2024).
tumor (continued). "This translocation results in the overexpression of GLI1 protein, a phenomenon also observed in various neoplasms, activating the hedgehog signaling pathway, which is crucial in gastrointestinal development." (PMID 38732067, 2024). "This appears to be at odds with the finding that epidermal transgene of Gli1 is sufficient to develop other 4 types of human BCC-like neoplasia in addition to superficial BCC47." (PMID 38307877, 2024). "In adult human tissues, GLI1ΔN mRNA was expressed with wild-type GLI1 at an approximate 1:1 ratio, but a generally lower and variable expression pattern of GLI1ΔN mRNA was observed in tumor cell lines." (PMID 37009804, 2023). "For example, overexpression of Shh was observed in CD133+ cells and accelerated tumor growth while inhibition of Shh or shRNA knockdown of Shh delayed tumor growth and downregulated Ptch1 and Gli1." (PMID 37274223, 2023). "HH pathway inhibition using cyclopamine has been shown to suppress GLI1 activation and to significantly enhance tumor radiosensitivity." (PMID 38020914, 2023). "In contrast to wild-type GLI1, tGLI1 specifically targeted CD24, an invasion-associated gene, inducing its transcription and was involved in increased tumor aggressiveness by promoting GBM cell motility and invasiveness." (PMID 37009804, 2023). "Compared with the DU145-RCC2 group, the tumor size and tumor volume in the DU145-RCC2 + GANT61 group were significantly decreased, indicating that inhibiting Gli1 reversed the effect of RCC on tumor growth." (PMID 38008751, 2023). "A promising therapeutic agent is GANT-61, which directly binds to the transcription factor GLI1/2, inhibits tumor cell proliferation and suppresses tumor formation in many preclinical studies." (PMID 37488121, 2023). "ADAR1, in conjunction with Glioma-associated oncogene-1 (GLI1), facilitates the substitution of R/G at position 701, which has been strongly associated with multiple tumours." (PMID 37845675, 2023). "Recent studies have shown that PAMD can down-regulate the expression of Shh, Ptch1, Smo and Gli1, key loci of the Hedgehog signalling pathway, and inhibit the growth of tumour cells, thus achieving anti-tumour effects." (PMID 36985672, 2023). "We examined the effect of a nuclear-residing Gli1 mutant on USP44 overexpression-mediated tumor inhibition." (PMID 38097536, 2023). "Herein, we demonstrated that UHRF1 functions as an epigenetic regulator that reprograms CSCs toward differentiation and tumor suppression via GLI1/Hedgehog and Wnt signaling." (PMID 37380646, 2023). "There was a significant positive correlation between FUNDC2 and GLI1 in TNBC tumor tissues (R=0.552,P<0.001)." (PMID 37700593, 2023). "This is further substantiated by a significant increase in the steady-state transcript levels of GLI1 in irradiated tumor cells." (PMID 37380890, 2023). "TAMs‐released CCL22 activates intratumoral CCR4/FAK/AKT axis, which induces the phosphorylation of Gli1 Ser112/Thr115/Ser116 sites, and stimulates Gli1 activity to induce the stemness and metastasis of tumor cells." (PMID 37846367, 2023). "There was strongly positive correlation between the level of intratumoral Gli1 and some clinical factors, like T/N status or tumor stage." (PMID 37846367, 2023). "GLI1 is well-known for its role in promoting the activation of the Hedgehog pathway, which ultimately contributes to tumour growth and progression." (PMID 37845675, 2023). "To gain a better understanding and to expand upon this observation, we irradiated tumor cells and stained for GLI1, POLR1A, and TCOF1." (PMID 37380890, 2023). "SHH overexpression was observed in OSCC, whereas expression of PTCH1 and GLI1/2 was noted in the vascular cells in the front of the tumor." (PMID 37626893, 2023). "Overexpression of Sloan–Kettering viral oncogene homolog (Ski), a protein which can function both as an oncoprotein and a tumor suppressor gene, leads to increased expression of Shh pathway components, such as Shh, Ptch-1, Smo, Gli1, and Gli2." (PMID 37815662, 2023).
tumor (continued). "We also conducted H&E and IHC staining for Ki-67, pERK, p21, KRASG12D, and Gli1 in orthotopic tumor tissues from each treatment group." (PMID 37872156, 2023). "In tumor cells, TCOF1 is a nucleolar protein that is important for RiBi and promotes nucleolar translocation of glioma-associated oncogene 1 (GLI1)." (PMID 38002277, 2023). "We found that tumor size and tumor weight were significantly increased in RCC2 overexpressed mice but decreased to normal levels after inhibiting with Gli1." (PMID 38008751, 2023). "Similar to UHRF1, high expression of GLI1 in cancerous tissues was also related to advanced tumor stage, poor histological differentiation, and adverse prognosis." (PMID 37380646, 2023). "Since Gli1 is the important tumor‐promoting transcriptional factor and therapeutic target, we utilized the Gli‐dependent luciferase reporter system for evaluating effects of TAMs‐released CCL22 on the intratumoral Gli1 activity and its nuclear location." (PMID 37846367, 2023). "The MALAT1-GLI1 fusion gene and upregulated GLI1 protein expression were also detected in some cases of this tumor, and the structure of the fusion gene was consistent with that of gastroblastoma." (PMID 37658451, 2023). "In Heller’s report, enhanced hedgehog signaling due to PTCH heterozygosity indirectly enhanced tumor-induced bone resorption; Ling also demonstrated that the inhibition of GLI1 maintained bone mass." (PMID 37929702, 2023). "By blocking the HH pathway using cyclopamine, we observed a decrease in GLI1 activation and an increase in tumor sensitivity to RT." (PMID 38020914, 2023). "The inhibition resulted in decreased expression of Ptch1 and Gli1, increased level of apoptosis, and decreased tumor weight and volume." (PMID 37815662, 2023). "SMO inhibition causes the transcription factors GLI1 and GLI2 to remain inactive, preventing tumour-mediating genes’ expression within the Hedgehog pathway." (PMID 37240278, 2023). "Regarding the expressions of Gli1 and Gli2, we observed Gli1 and Gli2 expressions in the tumor tissue in the bone marrow in addition to SHH expression." (PMID 37240209, 2023). "Immunohistochemical analysis of FUNDC2 and GLI1 expressions in tumor tissues showed a positive correlation between them." (PMID 37700593, 2023). "We performed Gli1 in situ hybridization on pre-, post-vismodegib, and the recurrent tumor samples and found similar Gli1 expression in all three samples." (PMID 36455049, 2022). "Previous studies have demonstrated the effect of GLI family zinc finger 1 (GLI1) inhibition on tumor growth and apoptosis." (PMID 35406554, 2022). "We took advantage of the ability to discriminate between normal and tumor cells in our human scATAC-Seq and scRNA-Seq data via chromatin accessibility and expression of GLI1, respectively." (PMID 36473848, 2022). "When classified into molecular subtypes (luminal, HER2-enriched, and TNBC), TNBC samples showed higher GLI1 expression than the luminal tumor samples." (PMID 36046646, 2022). "Altogether, these data demonstrate a promotional role of stromal AR signaling in Gli1-expressing cells to support prostate epithelial oncogenesis and tumor initiation." (PMID 36323713, 2022). "Immunohistochemical analysis of GLI1 expression in a tissue microarray revealed significant correlations between GLI1 expression and advanced tumor stage and grade." (PMID 36046646, 2022). "Activation of Gli1 transcription factors beyond Smo contribute to the development of several types of tumours with elevated Gli1 activity." (PMID 36457847, 2022). "Given the histomorphology and the fusion identified the final diagnosis was malignant epithelioid neoplasm with GLI1 fusion." (PMID 35387638, 2022). "The downregulation of Gli1 significantly inhibited tumor growth and enhanced E-cadherin expressions." (PMID 35433472, 2022).
tumor (continued). "Most importantly, arsenic trioxide (ATO), an anticancer drug that inhibits cell growth by targeting GLI1, significantly inhibited the metastasis capability of EwS cells in vitro and reduced the tumor burden in 75% of stage III EwS patients." (PMID 35740349, 2022). "Using in vivo tissue recombination assays, we first examined if stromal AR action in Gli1-lineage cells acts as a tumor niche to support prostate epithelial oncogenesis." (PMID 36323713, 2022). "Immunohistochemical analysis from the tumor tissues of mice shows such nanocomplexes significantly downregulate Shh and its downstream effector Gli1 in the combined GEM+miR-345 treated group compared with the single gemcitabine-treated group." (PMID 35581586, 2022). "None of the clinical trials reported on the skin concentration of HHi, whereas the biological response (GLI1 mRNA) was explored in four trials, and the clinical tumor response was investigated in all seven trials." (PMID 36430669, 2022). "It has been shown that patient-derived ES cell lines (CHLA9, CHLA10, TC32, CHLA258, and TC71) and tumor samples are enriched with GLI1." (PMID 35454895, 2022). "Given the detrimental effects observed when Gli1, Gli2, and Gli3 are deleted at PanIN stages, we next tested how Gli1/Gli2/Gli3 KO fibroblasts impact invasive tumor growth." (PMID 35867772, 2022). "The inhibition of tumor growth was accompanied by downregulation of GLI1 mRNA levels, indicating that the “Compound 5” strongly suppresses Hh signaling in vivo." (PMID 35163655, 2022). "In lung adenocarcinoma (LAC), KRAS and vascular endothelial growth factor (VEGF) receptor, NRP2, trigger MAPK/ERK/Gli1 signaling cascade to promote tumor progression." (PMID 35433472, 2022). "This tumor suppression activity occurred via direct targeting the transcription factor Gli1 and inhibition of the expression of the Gli1 target genes γ-catenin and BCL-2." (PMID 35682549, 2022). "Strikingly, co-injection of tumor cells with Gli1/Gli2/Gli3 KO fibroblasts promotes tumor growth to the same degree as parental Gli1 KO fibroblasts and WT control fibroblasts." (PMID 35867772, 2022). "Initially, identified from cellular screening assays in 2007, GANT58 and GANT61 were demonstrated to be selective inhibitors of Hh-driven tumor growth because of their capacity to downregulate the transcriptional activity of Gli1 and Gli2." (PMID 36517618, 2022). "NF-κB(p65), SHh and GLI1 were expressed in all tissues analyzed, showing higher NF-κB(p65) and GLI1 expression levels in tumor vs. normal samples." (PMID 35805202, 2022). "Conversely, antagonizing GLI targets in tumor cells either by knocking down Gli1 or over-expressing a constitutive GLI3 repressor increases tumor cell death and reduces colony formation." (PMID 35867772, 2022). "Immunohistochemical staining of tumor cells showed intense nuclear staining with labeled anti-Gli1 antibody in the two patients." (PMID 35457572, 2022). "In contrast, Gli1/Gli2/Gli3 KO fibroblasts recruit MDSCs and exclude NK cells, leading to sustained tumor growth." (PMID 35867772, 2022). "Given the proximity of prostatic Gli1-lineage FB and basal cells, these data demonstrate a specific role for stromal AR in Gli1-lineage cells in regulating oncogenesis and tumor development initiated by prostatic basal epithelial cells." (PMID 36323713, 2022). "To study the role of Gli1/Gli2/Gli3 in tumor growth, we performed tumor implantation experiments with Gli KO pancreatic fibroblasts." (PMID 35867772, 2022). "Twenty-one days of topical CUR-61414 treatment resulted in reduced Gli1 expression and significant tumor remission, and four days of vitamin D3 treatment led to reductions in Gli1 expression and tumor proliferation as measured by Ki67 protein levels." (PMID 36430669, 2022).
tumor (continued). "Gli1 is usually upregulated at the HNSCC tumor-stroma crossover after irradiation and assists in stroma-mediated radio-resistance, which can be reduced by pharmacological inhibition." (PMID 36517618, 2022). "On immunohistochemical staining, tumor cell nuclei showed intense staining with labeled anti-Gli1 antibody." (PMID 35457572, 2022). "In immunohistochemical examinations of the resected tissues, tumor cells showed intense nuclear staining with labeled anti-Gli1 antibody." (PMID 35457572, 2022). "In contrast, knockdown of GLI1 in gefitinib-resistant PC9 cells resulted in significant reductions in tumor volume and weight, as well as a remarkable increase in TUNEL-positive tumor cells." (PMID 35154464, 2022). "In NSCLC, Pristimerin affects the maturation of tumor angiogenesis by regulating the translocation of its downstream gene (Gli1) to the nucleus through HH signaling." (PMID 35433472, 2022). "Itraconazole markedly decreased cell proliferation by 45% (measure by Ki67 tumor proliferation), Hh pathway activity by 65% (measured by GLI1 mRNA expression), and tumor area by 24%." (PMID 35954384, 2022). "In this study, using in vivo tissue recombination assays and newly generated mouse models, we examined if stromal AR signaling in Gli1-lineage cells acts as tumor niches in prostate oncogenesis." (PMID 36323713, 2022). "Hh and Wnt pathways activation was assessed by immunohistochemistry (Gli1 and beta-catenin) on corresponding tumor tissues, and by plasma concentrations of Shh and Wnt (Wnt1, Wnt2 and Wnt3) at ICI introduction and at the first clinical evaluation." (PMID 33807552, 2021). "Among the 14 available tumor biopsies, nuclear expression of Gli1 was observed in 57.1% (8/14) of patients’ biopsies." (PMID 34970481, 2021). "To confirm Shh signaling pathway activation in the tumor tissue, we analyzed GLI1 gene expression using RNA-seq and confirmed that GLI1 mRNA was expressed at a significantly higher level compared with other analyzed samples." (PMID 34131151, 2021). "To understand if there is a correlation between circulating Shh levels and the activation of the Hedgehog pathway in HCC, we performed immunostaining on the sections of the tumor tissue for the expression of GLI-1 and PTCH1." (PMID 34692546, 2021). "Ectopic GLI1 activation in the mouse pancreas accelerated K-RAS driven tumor formation, underscoring the importance of GLI transcription factors in pancreatic tumorigenesis." (PMID 33494284, 2021). "According to Wilcoxon test, both FGFR1 (p = 0.0001) and GLI1 (p = 0.0001) were significantly overexpressed in tumor samples compared to their respective controls." (PMID 34722544, 2021). "A higher expression level of GLI1 was detected in OS tumor tissues as compared to the normal bone tissues." (PMID 34659557, 2021). "Among all tumor samples, the overall accordance rates, which combine the results of Gli1-negative and Gli1-positive samples, between Gli1 and BMI1 or SOX2 expression were 85% and 84%, respectively." (PMID 33499351, 2021). "Among all patients included (n = 63), expression of Gli1 in IHC was evaluated in 36 patients (57.1%) with enough tumor tissue available." (PMID 33807552, 2021). "Collectively, we demonstrated that overexpression of GLI1 in AML cells promotes tumor growth and upregulates cell cycle regulators and the PI3K/AKT pathway in a xenograft model." (PMID 33658491, 2021). "In vitro studies and animal models demonstrate the targeted inhibition of hedgehog signaling and the antitumor activity of sonidegib; oral administration of sonidegib in mouse models resulted in complete suppression of GLI1 expression and tumor regression." (PMID 34966484, 2021). "Fbxl17 mRNA was found to be significantly increased in the SHH-subtype MB and the levels of Fbxl17 and Gli1 positively correlated; depletion of Fbxl17 reduced Hh signaling through stabling Sufu, attenuated cancer cell proliferation and MB tumor growth." (PMID 34948134, 2021).